CRP (C-reactive protein)
Diseases named in the same sentence as CRP in open-access papers (continued):
Sharing a sentence is not in itself a finding about the gene and the disease.
heart failure (continued). "Markers of inflammation are known predictors of HF and cardiovascular disease, but the prognostic value of hs-CRP in moderate or severe sTR and HF has not been described yet and warrants further investigation as a potential biomarker in heart failure." (PMID 36757905, 2023). "Focusing on the guiding role of c-reactive protein (CRP) could function in the future prevention and treatment of heart failure." (PMID 36882679, 2023). "Elevated levels of c-reactive protein (CRP) and erythrocyte sedimentation rate (ESR), RF, ACPA and inflammatory cytokines may contribute to the progression of heart failure in RA." (PMID 36618407, 2022). "Similarly, a large EWAS meta-analysis on serum C-reactive protein (CRP), an inflammation biomarker predicting heart failure, identified 58 CpG sites related to CRP levels." (PMID 32211026, 2020). "SI was shown to increase the expression levels of Nrf2 and SOD and to reduce the expression of C-reactive protein, 8-isopropanol, MDA, IL-6, and TNF-α in patients with heart failure, improving the antioxidant capacity of patients with IC by upregulating Nrf2 and treating heart failure." (PMID 33062142, 2020). "In contrast, in a parallel study, a significant decrease in CRP was observed in women (but not men) suffering from heart failure who consumed tomato juice for a month." (PMID 30991720, 2019). "In 149 patients (65.8% men, median age 49.7 years) with heart failure from nonischaemic cardiomyopathy, the biomarkers neopterin and C-reactive protein were tested at the time of diagnosis." (PMID 31861167, 2019). "Second, a positive correlation between BNP and C-reactive protein was observed in cancer patients without heart failure." (PMID 29457529, 2018). "Heart failure, age, serum sRAGE (model 1) and serum esRAGE (model 2) independently predicted persistent AF, while C-reactive protein and renal impairment did not." (PMID 27627677, 2016). "It appears that TLR4 is particularly important for continuous monocyte activation in heart dysfunction, and that TLR4 overexpression is accompanied by secretion of proinflammatory cytokines such as CRP and TNF-α, as well as a known biomarker of cardiac failure—pro BNP." (PMID 26030867, 2015). "Results did not change markedly after additional adjustment for heart failure, partnership status or the inflammatory biomarker C-reactive protein." (PMID 24324579, 2013). "Results were not markedly changed when multivariable-adjustment also incorporated heart failure, partnership status or CRP concentrations (data not shown)." (PMID 24324579, 2013). "Furthermore, in heart failure patients with preserved ejection fraction, HDL-C/CRP ratio was found to be a valuable marker for predicting all-cause death and cardiac death and correlated with left ventricular diastolic function and right ventricular systolic function." (PMID 40709335, 2025). "Similarly, wearable electrochemical sensors for detecting cardiac biomarkers, such as troponin, brain natriuretic peptide (BNP), and C-reactive protein (CRP), offer early warning signs of MI, heart failure, and inflammation, facilitating timely interventions and improving patient outcomes." (PMID 40110293, 2025). "As a result, the negative prognostic impact of high CRP levels in heart failure may be particularly pronounced when CA125 is also elevated, highlighting the interplay between inflammation and fluid retention." (PMID 40894478, 2025). "Several studies have demonstrated that CRP levels rise rapidly after myocardial necrosis and remain elevated for several days, suggesting its utility not only in predicting AMI development, but also in forecasting recurrent infarction, heart failure, arrhythmias, and mortality." (PMID 41200636, 2025). "Therefore, reducing levels of CRP, TNF-α, and IL-6 in heart failure patients may help to reduce heart failure symptoms and improve the overall health of heart failure patients." (PMID 41179565, 2025).
heart failure (continued). "C-reactive protein categories were compared via negative-binomial/Cox regression for subsequent healthcare resource utilization and occurrence of major adverse cardiovascular events, heart failure hospitalization, and death." (PMID 39211962, 2024). "Similarly, in the Phase III ATTACH trial of another TNF-α antibody, infliximab, the percentage of death and heart failure-related hospitalization were not improved, although plasma levels of C-reactive protein (CRP) and IL-6 decreased after each injection." (PMID 35844550, 2022). "In addition, the interleukin-1β inhibitor reduced hospitalization for heart failure (HHF) and the composite of HHF or heart failure-related mortality in patients with prior myocardial infarction and elevations in the high-sensitivity C-reactive protein." (PMID 35997393, 2022). "Moreover, TIMP-1 has been found to be a predictor of the new onset of CKD and heart failure, regardless of age, gender, and biomarkers of systemic inflammation (c-reactive protein and brain natriuretic peptide)." (PMID 31963569, 2020). "Though increased expression of TGF-β and NF-κB were observed in angiotensin II-induced inflammation and during heart failure, it is not clear if CRP also induce increased expression of NF-κB and TGF-β to promote the onset of AF following a similar pattern as being observed in the glioblastoma cells." (PMID 31391207, 2019). "However, normal CRP concentration and normal WBC and NEUT can also be present in heart failure." (PMID 29573742, 2018). "However, when we analyzed other risk factors and parameters related to the extent of heart failure, AST, uric acid, CKMB, CRP, and LVEF were not well balanced among subgroups, and so the logistic regression was given." (PMID 23781119, 2013). "Moreover, a recent study found a significant positive correlation between the plasma BNP and serum CRP levels in cancer patients as well as cancer model mice without overt heart failure, linking also cancer-related chronic inflammation and natriuretic peptides." (PMID 28946871, 2017). "Other analyzed biomarkers (troponin T, creatine kinase, creatine kinase myocardial band, C-reactive protein, H-FABP) were not specific for TC but for other several diseases involving heart failure and the consequent state of inflammation." (PMID 36013193, 2022). "Other characteristics such as leukopenia, high levels of ferritin, C-reactive protein (CRP) and ventricular natriuretic peptide (a marker of heart failure), as well as low platelet count are not characteristic of KD." (PMID 34677484, 2021). "The results showed that CP value was well correlated with the extent of heart failure, and this correlation was independent of AST, uric acid, CKMB, LVEF, and even C-reactive protein which is a sensitive marker of inflammation." (PMID 23781119, 2013). "The SAFO trial included a substantially smaller number of participants than the Edinburgh and ARREST cohorts, applied more stringent inclusion and exclusion criteria (excluding MRSA infection, moderate to severe heart failure, and IDU), and did not record baseline CRP." (PMID 38916975, 2024). "Additionally, prior studies have shown a strong relationship between elevated CRP levels and the hospitalization of HF patients, regardless of the severity of CHD, medication use, baseline heart failure, or subsequent MI events." (PMID 36882679, 2023). "Among the rest of the factors that could have independent prognostic value, only CRP, LDH and heart failure had statistically significant coefficients but did not improve the overall performance of the model." (PMID 35149742, 2022).
viral infections (509 papers, 2005 to 2026). "HRV accounted for 72.5% of the detected viruses, and viral infection was associated with a greater risk of exacerbation (OR 2.26), higher symptom scores, and elevated C-reactive protein (CRP) levels." (PMID 40155903, 2025). "PCT can effectively distinguish between bacterial and viral infections, and its diagnostic sensitivity for NS is greater than that of CRP." (PMID 39886481, 2025). "The ROC analysis for distinguishing viral infections from mixed infections revealed that MxA and its combinations with CRP or other markers had poor diagnostic performance." (PMID 40046054, 2025). "Theoretically, bacterial infections can increase WBC and significantly decrease CRP, but viral infections can cause a decrease in WBC and a slight increase in CRP." (PMID 38306568, 2024). "CRP is an acute phase reactant that generally increases to higher levels with bacterial compared to viral infection, and MxA is a derivative of interferon α/β associated with viral infection." (PMID 38708643, 2024). "Elevated levels of CRP are commonly associated with viral infections, with research showing that about 62.8% of individuals with respiratory viral infections exhibit abnormal CRP levels." (PMID 39840216, 2024). "Bacterial infections usually determine a marked increase of CRP, while viral infections are associated with a mild increase in CRP levels." (PMID 36836679, 2023). "Although CRP lacks diagnostic specificity, it has been widely employed to differentiate between bacterial and viral infections and to classify bacterial infections based on severity." (PMID 39554800, 2023). "The integration of CRP for identifying bacterial infections and MxA for identifying viral infections into a unified diagnostic test holds the potential to reliably distinguish between bacterial and viral infections." (PMID 38202172, 2023). "In contrast, increasing studies have shown that excessively high CRP level was a risk factor for virus infection’s severity or fatal outcome, including influenza." (PMID 36275680, 2022). "On the other hand, it is well known that CRP is a marker for systemic inflammation already associated with severe disease in bacteria or virus infections." (PMID 34960595, 2021). "For instance, high expression of CRP is associated with bacterial or viral infections and was also reported to be significantly correlated with an increased probability of developing the severe form of the disease." (PMID 34260589, 2021). "ESR and CRP elevations are linked to an inflammatory response and cytokine storm triggered by viral infection." (PMID 34514172, 2021). "The CRP2 and especially CRPv further helped to differ between bacterial and viral infections, with a rapid rise in CRP associated with bacterial infections." (PMID 34863104, 2021). "Marked elevation of CRP levels is strongly associated with infection, including both bacterial infection and viral infection, although a stronger association exists for bacterial infection." (PMID 33019760, 2020). "It is commonly considered that mild inflammation and viral infections cause elevation of CRP in the 10–40 mg/L range." (PMID 33266250, 2020). "By contrast, interferon α significantly inhibits IL‐6‐induced CRP expression in hepatocytes, explaining why viral infections cause only modest elevations of CRP." (PMID 32246830, 2020). "In COVID-19 infections, CRP levels that are minimally elevated (e.g., between 10 and 20 μg/mL) can be diagnostic of mild viral disease." (PMID 32588812, 2020). "Several previous studies have suggested viral infection as a possible cause of AE-IP and there has been a report indicating that the CRP level is a significant prognostic factor in AE-IP." (PMID 31307466, 2019). "HNL and CRP have mainly been used as diagnostic tools for distinguishing bacterial from viral infections." (PMID 30834110, 2019). "C-reactive protein (CRP) and myxovirus resistance protein A (MxA) are associated with bacterial and viral infections, respectively." (PMID 28991170, 2017).
viral infections (continued). "Using a small sample of capillary whole blood, FebriDx provides measurements of CRP and MxA, biomarkers that are associated with bacterial and viral infections, respectively." (PMID 28991170, 2017). "The common causes of false-positive CRP values in neonates are surgery, immunizations, and severe viral infections such as herpes and rotavirus." (PMID 27689072, 2016). "Although bacterial infections are commonly characterized by the induction of IL-6 and CRP, viral infections are generally associated with marked elevation in plasma IL-18 and ferritin with concomitant low circulating CRP levels." (PMID 27977798, 2016). "We will also test the potential role of systemic inflammation, as reflected in levels of high-sensitive CRP (hsCRP), in the association between viral infection and cognitive function." (PMID 24983885, 2014). "Both viral infections were also associated with a significantly lower CRP-level compared to malaria or bacterial infections." (PMID 24755844, 2014). "Univariate analysis showed that a high levels of CRP and neutrophils were associated with bacterial infections, while VL positivitiy was more diagnostic for viral infections in febrile children." (PMID 24764729, 2014). "In addition, CRP is currently used clinically as a diagnostic marker for infectious diseases, but CRP increases slightly during viral infection and significantly during bacterial infection." (PMID 40158620, 2026). "By guiding the allocation of limited diagnostic and therapeutic resources, CRP testing, which is readily available in most clinical care settings, could improve triage and management during outbreaks of viral infections." (PMID 39877415, 2025). "Analysing the association between CRP levels and viral infection, the odds ratio (OR) for CRP was 0.974 (95% CI: 0.964–0.984, p < 0.001), indicating that higher CRP levels were associated with a lower probability of a viral infection." (PMID 41065831, 2025). "CRP, which is primarily used to differentiate bacterial from viral infections, demonstrates moderate diagnostic performance with receiver operating characteristic curve (AUC) values ranging from 0.6 to 0.85 across various studies, highlighting its limited accuracy as a standalone marker." (PMID 39861921, 2025). "This study, in contrast, targets a primary care environment and emphasizes the diagnostic interplay between LUS and CRP to differentiate bacterial from viral infections, aiding in clinical decision-making and probably reducing unnecessary antibiotic prescriptions." (PMID 39407829, 2024). "Thus, elevated serum levels of CRP, a widely used clinical biomarker of systemic inflammation, have also been associated with severe viral infection." (PMID 39916956, 2024). "According to textbooks, viral infections may cause a decrease in the ratio of white blood cells to neutrophils and a slight increase in C-reactive protein." (PMID 38306568, 2024). "One clinician argued for a biomarker to identify ‘risk of deterioration’ aiming for ‘something better than CRP’ that could be performed at home to distinguish bacterial or viral infection rapidly." (PMID 41220810, 2024). "Another important question arises: CRP is supposed to be an acute-phase reactant with human origin, and data highlight that it is elevated in systemic inflammation, but why do viral infections that are believed to be more pathogenic and harmful show relatively lower CRP levels?" (PMID 37873776, 2023). "In general, a mild viral infection usually results in either mildly increased or unchanged CRP levels, but a severe viral infection could cause extensive tissue damage, resulting in a significant increase in the CRP levels." (PMID 37143532, 2023). "Viral infections were associated with a lower increase in CRP levels than bacterial infections." (PMID 39554800, 2023).
viral infections (continued). "This cardiac damage is associated with increased interleukin-6 and C-reactive protein and may be caused by systemic inflammation and cytokine storm caused by viral infection." (PMID 35982484, 2022). "In myocarditis, most frequently caused by viral infection, elevated CRP levels are common." (PMID 35407379, 2022). "Some people considered that CRP levels were higher in bacterial infections than in viral infections, but the others suggested that CRP may be associated with viral infections as well as mixed viral/bacterial infections of AECOPD." (PMID 35400078, 2022). "The increase of CRP may indicate the state of inflammatory reaction and the degree of damage to the immune system caused by viral infection." (PMID 33853568, 2021). "We therefore speculated that lower fT3 levels and higher hs-CRP levels might be relevant to underlying virus infection in patients with FLM." (PMID 34926619, 2021). "Finally, we compared the diagnostic accuracy of the IMS to detect viral infections to CRP and PCT at cut-off values of <20 mg/L and <0.5 ng/ml respectively." (PMID 33647009, 2021). "The associations between SARS-CoV-2 viral load with levels of CRP and IL-6 results also indicate that active viral infection could contribute to the hyperinflammatory state that is a hallmark of severe COVID-1925." (PMID 33127906, 2020). "It is most likely that the presence of a ripple effect of bacterial and viral infections such as inflammatory reaction in the cochlea as reflected by an increase in CRP levels could cause NHS test failure." (PMID 30327582, 2018). "In addition to acute bacterial and viral infections, chronically elevated CRP levels are predictive of multiple diseases associated with inflammatory processes, e.g. cardiovascular disease (CVD)." (PMID 28922377, 2017). "Although the CRP level is widely used as an indicator of the severity of the disease in various infections, there are no reports associating high CRP levels with severe disease in NE or other viral infections." (PMID 25888018, 2015). "CRP could be a helpful tool to distinguish viral infections as cause of NMFI in the future however further studies to define more accurate thresholds are required." (PMID 24755844, 2014). "However, studies have supported that CRP acts as an indicator of bacterial and viral infection and it is linked with the apolipoprotein E4 allele." (PMID 24044608, 2013). "Although plasma CRP level is widely used as an indicator of the severity of the disease in various infections, there are no reports associating high CRP levels to a severe disease in NE or other viral infections." (PMID 20500875, 2010). "Conversely, CRP levels demonstrated a weak but significant inverse association (OR 0.98, 95% CI: 0.962–0.999, p = 0.036), suggesting that lower CRP values may be indicative of viral infection." (PMID 41065831, 2025). "Also, C-reactive protein, a primary marker of acute inflammation, with significantly elevated levels, is associated with systemic activation of the immune response in cases of viral infections or coinfections." (PMID 40427060, 2025). "Besides myocardial damage, viral infections often cause inflammation and tissue injury of other organs, particularly the respiratory organs leading to the upregulation of CRP production which can also contribute to higher levels of CRP among viral myocarditis patients." (PMID 39564010, 2024). "While short-term reductions of plasma CRP levels may be beneficial under certain circumstances, markedly lower CRP levels over prolonged periods of time may impair antimicrobial defense, and thus augmenting the risk of bacterial or viral infection." (PMID 37564640, 2023). "Thus, the presence of IFN-α per se could contribute to modest CRP levels during IFN-α associated disease flares of type I IFN-driven autoimmunity as well as in viral infections." (PMID 33584722, 2020).